CDC73 (cell division cycle 73)
Diseases named in the same sentence as CDC73 in open-access papers (continued):
Sharing a sentence is not in itself a finding about the gene and the disease.
cancer (40 papers, 2010 to 2025). A tumor composed of atypical neoplastic, often pleomorphic cells that invade other tissues. "Two genome-profiling analyses also specifically focused on sporadic PCs confirmed the high rate of CDC73 mutations associated with these malignant tumors." (PMID 34681865, 2021). "We report here for the first time the occurrence of oncocytic transformation in several tumors in a family pedigree, associated with HPT-JT syndrome, an inherited cancer-predisposing disorder caused by germline mutations in the CDC73 tumor suppressor gene." (PMID 34831144, 2021). "In the same way, PCs with mutations in the CDC73 gene overexpressed BC200 lncRNA compared to CDC73 wild-type carcinomas." (PMID 34638805, 2021). "Inactivating mutations in the cell division cycle-73 gene (CDC73) encoding nuclear tumor suppressor protein parafibromin have been identified in up to 80% of PC samples, rendering parathyroid tissue more prone to carcinoma formation." (PMID 40362680, 2025). "Germline mutation of CDC73 was exclusively found in carcinoma samples." (PMID 37121965, 2023). "Loss of H2BK120ub1 is an epigenetic change that has been shown in advanced cancers and, thus, may also be involved in CDC73 loss-derived parathyroid tumorigenesis, both in HPT-JT-related and sporadic tumors." (PMID 34681865, 2021). "Patient 9, classified as having a cancer-type APT, exhibited two distinct mutations within the genomic region of CDC73: a frameshift mutation (c.15delT) and a stop-gained mutation (c.376C>T)." (PMID 40434298, 2025). "In this review, we summarize the gene structure, biological functions, signaling pathways, and phenotypes of CDC73 knockout mice and the relationship of genetic and expression alterations in CDC73 with cancer." (PMID 36211470, 2022). "Mutations in CDC73 and CTR9 have been identified in cancer and telomere function is often affected in cancer." (PMID 29145644, 2018). "It is cautious to employ CDC73 mRNA to evaluate the clinicopathological behaviors and prognosis of cancers." (PMID 29221126, 2017). "A higher CDC73 mRNA expression was positively correlated with overall and progression-free survival rates of Her2-netagive cancer patients (p<0.05)." (PMID 29221126, 2017). "A higher CDC73 expression was found in gastric normal mucosa than that in cancer, even stratified into intestinal-, diffuse-, and mixed-type carcinomas by Lauren's classification (p<0.05)." (PMID 29221126, 2017). "CDC73, as part of the PAF1 complex (PAF1c), is known to be mutated in a variety of cancers like parathyroid carcinoma, breast carcinoma and colorectal carcinoma." (PMID 27462432, 2015). "Patient 14, also with a cancer-type APT, had a CDC73 missense variant (c.34A>G)." (PMID 40434298, 2025). "Inactivation of the CDC73 tumor suppressor gene is a genetic marker of risk for development of PCs, both in the context of HPT-JT syndrome (about 15% of cases) and as sporadic cancer." (PMID 34681865, 2021). "Finally, human CDC73 and CTR9 genes are frequently found mutated in cancer, and are the only PAF1 complex genes to be currently classified as tumour suppressors." (PMID 29145644, 2018). "Moreover, SHP-2 enhances β-catenin nuclear translocation via dephosphorylating CDC73 in liver cancer cells to promote the dedifferentiation of hepatoma cells, which finally promoted the expansion of cancer stem cells in cancer cell population." (PMID 29558404, 2018). "Stage-I, stage-III, T2 and T3 cancer patients with high CDC73 mRNA expression showed a long overall survival time than those with its low expression (p<0.05), while it was the same for progression-free survival in the patients with stage-III and -IV, T2, M0, and diffuse-type carcinoma (p<0.05)." (PMID 29221126, 2017). "In summary, up-regulated CDC73 mRNA expression in cancer and its positive correlation with aggressive behaviors and unfavorable prognosis might be due to a feedback reaction or its oncogenic function." (PMID 29221126, 2017).
cancer (continued). "In contrast, mutation of the human homologues of Cdc73 (HRPT2/CDC73 or parathrombin), loss of Ctr9, and over-expression of Paf1 have all been associated with cancer, and a parathrombin missense mutant both impaired nucleolar localization and promoted growth and survival of NIH3T3 cells." (PMID 22532828, 2012). "Hence, these data indicated that circ_0000140 might play an anti-cancer role by regulating the miR-182-5p/CDC73 axis." (PMID 32863766, 2020). "Therefore, CDC73 could potentially protect against cancer by promoting RNAPII-mediated ATR activity, leading to cell death in non-cycling cells with DNA damage." (PMID 30541148, 2019). "CDC73 is mutated in various types of cancer and absence of staining serves as a diagnostic marker." (PMID 27462432, 2015). "The mode of action of CDC73 in cancer formation and progression, however, remains largely unknown." (PMID 27462432, 2015). "In a similar manner to the PAF1 knockdown, CDC73 or CTR9 knockdown inhibited cell proliferation, reduced the expression levels of most cancer stem cell marker genes including LGR5 and ID1, and increased those of KRT20 and MUCs." (PMID 38182897, 2024). "In the analysis of key genes co-expression, we found the four genes (CDC73/CDC123/B4GALT1/CUL2) are most relevant to the expression of key genes and also related to the occurrence of many cancers." (PMID 35111402, 2022). "We identified cancer genes recurrently overexpressed across the cohort, e.g., MDM4 in six and CDC73 and TPR in five tumors, respectively." (PMID 36230794, 2022). "For example, the RNA splicing and processing theme involves 2,009 pSNVs in 652 genes, including 38 known cancer genes such as BRCA1, RBM15, CDK12, CDC73 and TOP1 (FDR p = 1.3e − 06, Fisher's exact test), as well as candidate cancer genes." (PMID 24089029, 2013). "In our cohort, no clinical or genetic data suggested MEN1-, MEN2-, or CDC73-related syndromes in the carcinoma cases, but genetic testing was not routinely performed, which is a limitation of our study." (PMID 40507262, 2025). "Among the 7 RNA, CDC73 and TRIB2 have been identified as biomarkers for cancer prognosis." (PMID 35751033, 2022). "However, they partly showed similar genomic profiles regarding gains on chromosome 16, 17p and 17qter, 20q11, 21q22 and 22.No losses spanning the CDC73 gene locus at 1q31.2 were detected among the carcinomas or in the atypical adenoma case." (PMID 23029479, 2012).
adenocarcinoma (2 papers, 2017). A common cancer characterized by the presence of malignant glandular cells. "Recently, we reported that CDC73 expression was higher in moderately- than well-differentiated adenocarcinoma at both mRNA and protein level, opposite to our finding." (PMID 29221126, 2017).
benign neoplasm (2 papers, 2022 to 2023). A neoplasm which is characterized by the absence of morphologic features associated with malignancy (severe cytologic atypia, tumor cell necrosis, and high mitotic rate). "Oppositely, CDC73 mutations were very rare in benign neoplasms." (PMID 36777354, 2023). "CDC73 germline mutation causing significant conformational alterations in the conserved C-terminal domain or parafibromin loss (identified as “high-impact mutations”) were substantially more frequently observed in PC patients than in all other individuals with benign tumor." (PMID 36211470, 2022).
hematologic malignancies (1 paper, 2020). "Interestingly, we observed one CDC73 VUS and one PV in two patients with hematologic malignancies." (PMID 33332384, 2020).
CDC73 also shares sentences with these, for which no sentence is quoted: ossifying fibroma of the jaw (4 papers); adenomyosis (2); autosomal dominant disease (2); Endocrine Neoplasia (2); familial benign hypocalciuric hypercalcemias (2); genetic disorders (2); kidney carcinoma (2); leiomyoma (2); medullary thyroid carcinoma (2); multiple endocrine neoplasia (2); pancreatic NET (2); acute lymphoblastic leukemia (1); adenomyoma (1); Anxiety (1); bone marrow failure syndrome (1); colorectal tumors (1); endometrial cancer (1); epulis (1); Fibroadenoma (1); fibrous dysplasia (1); hamartoma (1); head and neck squamous cell carcinoma (1); hematologic cancer (1); hereditary hyperparathyroidism (1); hereditary leiomyomatosis and renal cell cancer (1); hereditary renal cell carcinoma (1); Hypertension (1); hyperthyroidism (1); infection (1); inflammation (1).
A further 26 diseases each share a sentence with CDC73 in 1 paper.